ABHD12B (abhydrolase domain containing 12B)
Synonyms: C14orf29; BEM46L3; c14_5314
Tractability: No criterion of Open Targets' tractability assessment is met for any kind of drug.
Gene: Protein-coding gene on chromosome 14 (50,872,053 to 50,904,970, forward strand). Ensembl gene ENSG00000131969.
Subcellular location (Human Protein Atlas): Nucleoplasm
Gene Ontology:
Molecular function: phosphatidylserine lysophospholipase activity
Biological process: monoacylglycerol catabolic process; phosphatidylserine catabolic process
Cellular component: endoplasmic reticulum membrane
Genetic constraint (gnomAD): Loss-of-function variants: 38 observed, 43.39 expected, observed/expected ratio (o/e) 0.88, 90% interval 0.68 to 1.15. The upper end of that interval is the gene's LOEUF score, 1.15, which puts it in group 5 of 6, group 1 being the genes least tolerant of losing a copy. Missense variants: 420 observed, 374.07 expected, observed/expected ratio (o/e) 1.12, 90% interval 1.04 to 1.22. Synonymous variants: 152 observed, 137.44 expected, observed/expected ratio (o/e) 1.11, 90% interval 0.97 to 1.26.
Homologues: Orthologues: chimpanzee ABHD12B (99% identical), macaque ABHD12B (95% identical), dog ABHD12B (81% identical), pig ABHD12B (81% identical), rat Abhd12b (79% identical), mouse Abhd12b (75% identical), rabbit ABHD12B (73% identical), guinea pig ABHD12B (66% identical), tropical clawed frog abhd12b (44% identical), zebrafish abhd12 (38% identical), zebrafish si:ch211-117n7.7 (37% identical), zebrafish si:ch211-117n7.6 (34% identical), and 6 more. Paralogues in human: ABHD12 (42% identical), ABHD13 (21% identical), ABHD16A (20% identical), ABHD17A (20% identical), ABHD17B (19% identical), ABHD16B (18% identical), ABHD17C (18% identical).
Diseases named in the same sentence as ABHD12B in open-access papers:
ABHD12B is named in the same sentence as 6 diseases in open-access papers, as found by Europe PMC text mining. Sharing a sentence is not in itself a finding about the gene and the disease. The quoted sentences say what the papers report.
chronic periodontitis (2 papers, 2018 to 2022). A chronic inflammatory process that affects the tissues that surround and support the teeth. "Genome-wide association studies showed the relationship of NIN, ABHD12B, WHAMM, AP3B2, and SIGLEC5 with chronic periodontitis." (PMID 36360171, 2022). "Since the underlying molecular mechanisms of periodontitis are still unclear, the effects of the NIN, ABHD12B, WHAMM, AP3B2, and SIGLEC5 genes on periodontitis have not been elucidated." (PMID 36360171, 2022).
Obesity (2 papers, 2015 to 2025). Accumulation of substantial excess body fat. "In this study, we identified, for example, the genes ENPP1, CTSL, CIDE-C, and ABHD12B as potential causal genes for obesity, and further validation (e.g., by qPCR in a large human population) and investigation of these genes might lead to biomarkers for obesity." (PMID 26482556, 2015). "Furthermore, we detected several obesity candidate genes, for example, ENPP1, CTSL, and ABHD12B." (PMID 26482556, 2015).
breast carcinoma (1 paper, 2013). "In parallel studies for downregulated genes, we were able to identify seven genes with mutations in colon cancer (DPP10, PCSK2, ADAM33, RELN, CAPN13, ADAMTS1 and ADAMTS15), and five genes with mutations in breast carcinomas (MASP3, ABHD12B, TLL1, CPA3 and DPP6)." (PMID 24243807, 2013).
ABHD12B also shares sentences with these, for which no sentence is quoted: colon cancer (1 paper); embryonal carcinoma (1); seminoma (1).